PCDH1 (protocadherin 1)
Description:
May be involved in cell-cell interaction processes and in cell adhesion.
Synonyms: PC42; PCDH42
Tractability: Antibody: UniProt places it where antibodies can reach, with high confidence; its Gene Ontology location is reachable by antibodies, with high confidence; UniProt predicts a signal peptide or a membrane-spanning region. PROTAC: ubiquitination databases record sites on it; its protein half-life has been measured.
Gene: Protein-coding gene on chromosome 5 (141,853,090 to 141,879,246, reverse strand). Ensembl gene ENSG00000156453.
Subcellular location: Cell junction; Cell membrane
Subcellular location (Human Protein Atlas): Cell Junctions; Nucleoplasm; Nucleoli
Gene Ontology:
Molecular function: cell adhesion molecule binding; calcium ion binding
Biological process: cell adhesion; cell-cell signaling; nervous system development; homophilic cell-cell adhesion
Cellular component: cell junction; cell-cell junction; plasma membrane; anchoring junction; membrane
Genetic constraint (gnomAD): Loss-of-function variants: 23 observed, 72.69 expected, observed/expected ratio (o/e) 0.32, 90% interval 0.23 to 0.45. The upper end of that interval is the gene's LOEUF score, 0.45, which puts it in group 1 of 6, group 1 being the genes least tolerant of losing a copy. Missense variants: 1,214 observed, 1,669.8 expected, observed/expected ratio (o/e) 0.73, 90% interval 0.69 to 0.76. Synonymous variants: 647 observed, 696.08 expected, observed/expected ratio (o/e) 0.93, 90% interval 0.87 to 0.99.
Homologues: Orthologues: chimpanzee PCDH1 (99% identical), macaque PCDH1 (99% identical), rabbit PCDH1 (97% identical), dog PCDH1 (97% identical), pig PCDH1 (97% identical), guinea pig PCDH1 (96% identical), rat Pcdh1 (96% identical), mouse Pcdh1 (80% identical), tropical clawed frog pcdh1 (74% identical), zebrafish pcdh1a (65% identical), zebrafish pcdh1b (60% identical). Paralogues in human: PCDH7 (51% identical), PCDH9 (37% identical), PCDH11X (36% identical), PCDH11Y (35% identical), PCDH20 (22% identical), CDH23 (22% identical), DCHS1 (21% identical), DCHS2 (20% identical), CDHR2 (17% identical), CDH1 (16% identical), CDH2 (16% identical), CDH4 (16% identical), and 21 more.
Diseases named in the same sentence as PCDH1 in open-access papers:
PCDH1 is named in the same sentence as 46 diseases in open-access papers, as found by Europe PMC text mining. Sharing a sentence is not in itself a finding about the gene and the disease. The quoted sentences say what the papers report.
asthma (20 papers, 2011 to 2024). "Previous research has shown that common genetic variations in PCDH1 gene increases the risk of developing asthma and bronchial hyperresponsiveness." (PMID 34301314, 2021). "PCDH1 has been associated with asthma, a chronic inflammatory disorder of the airways characterized by wheezing, coughing, breathlessness, chest-tightness, bronchial hyperresponsiveness, and obstruction to airflow." (PMID 31583286, 2019). "Subsequent studies in Dutch, German, and Danish populations reported associations of different PCDH1 gene variants with multiple phenotypes of asthma as well as eczema." (PMID 27701444, 2016). "The expression of PCDH1 is aligned with the apical adhesion complex expression in airway epithelial cells hence association of PCDH1 with asthma is proposed to be through epithelial structural defects leading to BHR and is IgE independent." (PMID 27658857, 2016). "Previously, we identified protocadherin-1 (PCDH1) as a novel susceptibility gene for airway hyperresponsiveness (AHR) in asthma families." (PMID 24992194, 2014). "Because gene–passive smoking interactions have been found to be relevant for the association of PCDH1 with asthma, the contribution of PCDH1 gene variants to asthma might only become evident in the context of smoke exposure." (PMID 28583446, 2017). "Several single nucleotide polymorphisms (SNPs) in PCDH1 have been linked to asthma and BHR." (PMID 28583446, 2017). "The asthma gene PCDH1 encodes Protocadherin-1, a putative adhesion molecule of unknown function expressed in the airway epithelium." (PMID 27701444, 2016). "Importantly, we provide evidence that PCDH1 function is relevant for maintaining epithelial barrier and that loss of functional PCDH1 represents a potential mechanism for development of asthma and BHR." (PMID 27701444, 2016). "Protocadherin-1 (PCDH1) was recently identified as a susceptibility gene in asthma." (PMID 26227965, 2015). "The discovery of this mode of adhesion, likely used by all other members of the δ1 protocadherin family, along with our structures, might help in understanding the molecular mechanisms underlying PCDH1-related respiratory diseases such as asthma and hantavirus pulmonary syndrome." (PMID 31583286, 2019). "PCDH1 has been studied in asthma patients and was upregulated during the development of airway epithelial barrier." (PMID 37082114, 2022). "Another molecule, protocadherin 1 (PCDH1), expressed in bronchial epithelial cells, has emerged as a susceptibility gene for bronchial hyperresponsiveness and asthma in children." (PMID 36203653, 2022). "The hsa-mir-155-5p targets a well-known asthma gene, PCDH1, which encodes protocadherin-1, which is mainly expressed in the bronchial epithelium and lungs." (PMID 36264868, 2022). "A vast Danish research study demonstrated associations between a mutation on the gene that encodes protocadherin-1 (PCDH1) and asthma, wheezing, and atopic dermatitis in children." (PMID 34573894, 2021). "An interaction between PCDH-1 and passive exposure to smoke during childhood in the development of asthma was also suggested." (PMID 34573894, 2021). "The asthma gene PCDH 1, encoding protocadherin-1, is a cellular adhesion molecule which plays an important role in epithelial barrier formation and repair." (PMID 30510870, 2018). "Protocadherin-1 (PCDH 1) gene is recently got identified as a susceptible gene to be responsible for developing bronchial hyperresponsiveness and asthma." (PMID 30510870, 2018). "In recent years, genetic studies of bronchial epithelial cells have discovered several genes, such as protocadherin 1 (PCDH1), periostin (POSTN), serpin family B member 2 (SERPINB2), and chloride channel accessory 1 (CLCA1), associated with asthma phenotypes." (PMID 28725641, 2017). "Dysregulation of PCDH1 expression in asthma also leads to impaired differentiation of epithelial cells." (PMID 27658857, 2016).
asthma (continued). "Here, we characterize the localization, differential expression, homotypic adhesion specificity and function of PCDH1 in airway epithelial cells in asthma." (PMID 27701444, 2016). "Importantly, loss of PCDH1 reduced epithelial barrier function, both during establishment of the barrier as well as during epithelial repair after damage, indicating that dysregulation of PCDH1 might contribute significantly to loss of epithelial integrity in specific subgroups of asthma patients." (PMID 27701444, 2016). "In 2009, our group identified Protocadherin 1 (PCDH1) as a susceptibility gene for bronchial hyperresponsiveness (BHR) and asthma." (PMID 27701444, 2016). "Next, to compare PCDH1 expression and localization in asthma and controls we performed qRT-PCR and fluorescence microscopy in PBECs and immunohistochemistry on airway wall biopsies." (PMID 27701444, 2016). "In future studies, it will be important to study the expression and function of PCDH1 in larger numbers of subjects with varying asthma severity." (PMID 26227965, 2015). "The human chromosomal region 5q31–33, containing PCDH1, was previously linked to AHR and asthma in 95 ETS exposed families." (PMID 24992194, 2014). "In addition, various genes that are crucial in epithelial barrier homeostasis, like protocadherin 1 (PCDH1) and Cadherin-related family member 3 (CHHR3), have also been shown to be associated with asthma genetic studies." (PMID 36832296, 2023). "Recent genome-wide association studies have uncovered a link between gene polymorphisms in several junctional proteins such as PCDH1 (Protocadherin 1 gene) and CDHR3 (encoding cadherin-related family member 3) with asthma, as well as increased risk for severe viral infections." (PMID 28759570, 2017). "At present, more detailed information confirming the specific subcellular localization of PCDH1 in the airway epithelium is lacking and its contribution to asthma susceptibility is not fully understood." (PMID 27701444, 2016). "We hypothesized that PCDH1 is required for effective epithelial barrier formation and repair, and that expression is reduced in asthma." (PMID 27701444, 2016). "Among susceptibility genes detected by positional cloning, IRAKM may represent a potential biomarker for early onset of asthma whereas PCDH1 may be a potential biomarker in both children and adults." (PMID 27658857, 2016). "We tested whether PCDH1 was differentially expressed between asthma and control subjects by three approaches, using two sources of primary material." (PMID 27701444, 2016). "PCDH1 gene variants are reported to be associated with BHR, asthma and eczema." (PMID 27701444, 2016). "In this study, we tested the hypothesis that functional abnormalities due to PCDH1 dysregulation may affect epithelial barrier formation and thereby contribute to the pathogenesis of asthma." (PMID 26227965, 2015). "Interestingly, a strong linkage signal of PCDH1 with asthma and AHR was observed in families exposed to environmental tobacco smoke (ETS)." (PMID 24992194, 2014). "Since different PCDH1 gene variants were associated with specific asthma phenotypes including BHR positive, early onset, and non-allergic asthma, we proposed that PCDH1 may contribute to disease pathogenesis in subgroups of asthma patients." (PMID 27701444, 2016). "A drawback from our study is that we could not perform these studies in asthmatic subjects and controls stratified for the PCDH1 asthma susceptibility genotypes, since there was no informed consent to genotype these subjects." (PMID 27701444, 2016). "But, interestingly, in both asthma and CRS patients, low PCDH1 expression levels in the airway epithelium were observed in regions containing inflammatory cells, large-scale epithelial detachment, and widened intercellular spaces." (PMID 26227965, 2015).
asthma (continued). "Given the initial linkage of PCDH1 to AHR and asthma in cigarette smoke exposed families defined by a significant smoking history of the asthma proband of more than 5 packyears, we investigated whether Pcdh1 expression was regulated in a sub-chronic (5 days) smoke exposure model." (PMID 24992194, 2014). "Positional cloning and linkage analysis studies of AHR have identified two well-validated asthma candidate genes: ADAM33 and PCDH1." (PMID 23984888, 2013). "Expression of PCDH1 is not reduced nor delocalized in asthma even though PCDH1 contributes to homotypic adhesion, epithelial barrier formation and repair." (PMID 27701444, 2016). "To test our hypothesis, we characterized expression levels and localization of PCDH1 in ALI cultured PBECs and in airway wall biopsies from asthma patients and control subjects." (PMID 27701444, 2016). "Therefore, we cannot draw any conclusions regarding the regulation of PCDH1 isoforms during epithelial differentiation on ALI and between asthma and control subjects." (PMID 27701444, 2016). "Moreover, it is not known whether expression or localization of PCDH1 is altered in the airway epithelium of subjects with asthma compared to healthy controls." (PMID 27701444, 2016). "However, Nod1 was not represented on the platforms used for analyses on the A/J and SW strains and could thus not be evaluated in these data sets (also true for another asthma gene with consistent expression patterns, PCDH1)." (PMID 21699702, 2011).
pancreatic cancer (4 papers, 2019 to 2026). "Among such five genes, PCDH1 is the most effective tumor-associated gene, contributing to pancreatic cancer with abnormal promoter methylation status and participating in FGFR-associated signaling pathways." (PMID 31456818, 2019). "Protocadherin-1 (PCDH1), a member of the protocadherin family, has recently been implicated in multiple pathological processes, but its role in pancreatic cancer biology remains largely unexplored." (PMID 41602375, 2026). "scRNA-seq analysis and migration inhibition assays demonstrated that PCDH1 expression correlated with pancreatic cancer metastasis." (PMID 37957639, 2023). "Our findings suggest that PCDH1 is a promising tissue biomarker, and that these compounds can serve as potential therapeutic agents against pancreatic cancer." (PMID 37957639, 2023). "The key role of these compounds is to down-regulate PCDH1 expression and prevent pancreatic cancer metastasis." (PMID 37957639, 2023). "Taken together, patients with pancreatic cancer with high PCDH1 expression levels were predicted to have poor OS and DFS." (PMID 37957639, 2023). "The results of the cell migration assay suggest that PCDH1 play an important role in pancreatic cancer cell metastasis." (PMID 37957639, 2023). "The results showed that the expression levels of PCDH1 in the pancreatic cancer cells Panc-0813 and BxPC-3 were significantly up-regulated compared to those in the normal human pancreatic ductal cells hTERT-HPNE." (PMID 37957639, 2023). "The results showed a concentration- and time-dependent regulation of PCDH1 protein expression in pancreatic cancer cells, as determined using western blotting." (PMID 37957639, 2023). "We further investigated the role played by PCDH1 in regulating the side population (SP) phenotype, which has been identified in cultured pancreatic cancer cells and shows similar characteristics to cancer stem cells (CSCs)." (PMID 35864095, 2022). "Our results demonstrated that PCDH1 promoted p65 nuclear import, which activated the NF-κB pathway in pancreatic cancer cells and tissues, and that this activation was achieved through PCDH1 interaction with KPNB1, a widely studied nuclear transporter." (PMID 35864095, 2022). "After confirming is highly expressed in pancreatic cancer cells, IHC was performed to investigate PCDH1 protein levels in tumour tissue samples of patients, and the results showed that PCDH1 was highly expressed in tumour tissues of patients with pancreatic cancer." (PMID 37957639, 2023). "These novel molecular developments may provide new ideas for the treatment of pancreatic cancer with PCDH1." (PMID 37957639, 2023). "Flutamide may be a potential drug for the treatment of pancreatic cancer through the regulation of PCDH1 expression." (PMID 37957639, 2023). "Up-regulated PCDH1 promotes pancreatic cancer cell metastasis." (PMID 37957639, 2023). "Additionally, we found that some small molecules down-regulated PCDH1 expression and are potential drugs for the treatment of patients with pancreatic cancer." (PMID 37957639, 2023). "Moreover, PCDH1 was up-regulated in pancreatic tumour tissues compared to that in adjacent paired normal tissue samples from TCGA dataset." (PMID 37957639, 2023). "Thus, PCDH1 could be a potential biomarker for detecting pancreatic cancer and assessing the survival of patients with pancreatic cancer." (PMID 37957639, 2023). "By analysing the TCGA database, we found that the expression of PCDH1 was positively correlated with CCND1, CCNE2, VEGFA, MET, CD44 and CD133 expression in pancreatic cancer tissues." (PMID 35864095, 2022). "Together, these findings demonstrate that PCDH1 knockdown suppresses pancreatic cancer cell migration, whereas IGF-1 stimulation counteracts this effect, suggesting that PCDH1 may regulate cell motility at least in part through the IGF-1–associated signaling pathway." (PMID 41602375, 2026).
pancreatic cancer (continued). "However, PCDH1 down-regulation did not affect the cell viability of pancreatic cancer cells, which is consistent with previous knockdown results." (PMID 37957639, 2023). "Not all the inhibitors reduced PCDH1 expression in pancreatic cancer cells." (PMID 37957639, 2023).
hantavirus infection (3 papers, 2019 to 2023). "Herein, we link the inter-species sequence variations in PCDH1 and mammalian host-specific receptor usage by hantaviruses to pinpoint sequences that could influence susceptibility to hantavirus infection." (PMID 37488123, 2023). "In either case, the molecular details provided by our PCDH1 EC1-4 structure may guide drug discovery strategies aimed at reducing or blocking hantavirus infections." (PMID 31583286, 2019). "More work is needed to test this idea as well as simpler (e.g., PCDH1 down-regulation) and more complex scenarios (e.g., Gn/Gc-induced changes in PCDH1 conformation or transmembrane signaling), through which hantavirus infection could perturb PCDH1’s endogenous functions in the mammalian airway." (PMID 37488123, 2023). "More recently, we identified protocadherin-1 (PCDH1) as a critical determinant of attachment, entry, and infection by New-World hantaviruses, but not their Old-World counterparts, in primary human microvascular endothelial cells, which are major targets of hantavirus infection in vivo." (PMID 34232859, 2021).
pancreatic ductal adenocarcinoma (3 papers, 2022 to 2026). An infiltrating adenocarcinoma that arises from the epithelial cells of the pancreas. "Our study identifies PCDH1 as a stemness-linked oncogene in pancreatic ductal adenocarcinoma (PDAC)." (PMID 41602375, 2026). "PCDH1 not only induced Wnt signaling activation in PCa but also the progression of pancreatic ductal adenocarcinoma via NF-κB signaling." (PMID 37576552, 2023).
airway hyperresponsiveness (2 papers, 2014 to 2019). "Protocadherin-1 (PCDH1) is a novel susceptibility gene for airway hyperresponsiveness, first identified in families exposed to cigarette smoke and is expressed in bronchial epithelial cells." (PMID 24992194, 2014). "Variants in a disintegrin and metalloprotease 33 (ADAM33) and protocadherin-1 (PCDH1) were reported to be involved in airway hyperresponsiveness and airway remodeling." (PMID 30906771, 2019). "Cigarette smoke exposure for 4 consecutive days markedly reduced Pcdh1 mRNA expression in lung tissue (3 to 4-fold), while neutrophilia and airway hyperresponsiveness was induced." (PMID 24992194, 2014). "Future studies on the function of Protocadherin-1, using novel knockout and/or transgenic approaches, and its interaction with environmental factors such as CS exposure are required to provide novel insights into the origins of airway hyperresponsiveness." (PMID 24992194, 2014).
allergic disease (2 papers, 2023). An immune response that occurs following re-exposure to an innocuous antigen, and that requires the presence of existing antibodies against that antigen. "And the protection of corticosteroids may be associated with the allergic disease susceptibility gene, protocadherin-1." (PMID 36724763, 2023).
chronic rhinosinusitis (2 papers, 2015 to 2016). Chronic form of sinusitis. "We studied PCDH1 function by siRNA-mediated knockdown and analyzed nasal or bronchial tissues from 16 patients with chronic rhinosinusitis (CRS) and nine patients with bronchial asthma for PCDH1 expression." (PMID 26227965, 2015).
epilepsies (2 papers, 2011 to 2024). "In conclusion, these results extend the mutational and clinical spectra associated with PCDH1 9-related epilepsies and show that mutations in PCDH19 are a frequent cause of epilepsy in females and should be considered even in absence of family history and/or mental retardation." (PMID 21053371, 2011). "We discovered the combinatorial expression of Protocadherin-19(Pcdh19), a protein involved inPCDH19-clustering epilepsy, with Pcdh1, Pcdh9 or Cadherin 13 (Cdh13) in excitatory neurons." (PMID 38629124, 2024).